TSLP (thymic stromal lymphopoietin)
Diseases named in the same sentence as TSLP in open-access papers (continued):
Sharing a sentence is not in itself a finding about the gene and the disease.
asthma (continued). "In a subset of patients with severe asthma, TSLP expression remains enhanced, independent of treatment with high-dose inhaled or oral corticosteroids." (PMID 37628907, 2023). "IGC treatment (p = 0.07) and any admission for asthma (p = 0.07), tended to be more frequent in children with TSLP detection, although without reaching statistical significance." (PMID 36694181, 2023). "Tezepelumab is a human monoclonal antibody that specifically binds to TSLP and blocks its interaction with the receptor complex, and is approved for severe asthma without phenotypic (e.g., eosinophilic or allergic) or biomarker restrictions." (PMID 37377958, 2023). "Among biologics, dupilumab and tezepelumab target IL-4Rα and TSLP, respectively, and IL-4 and TSLP acted on ILC2s directly in in vivo or in vitro studies; therefore, these biologics might attenuate ILC2-mediated asthma." (PMID 37371472, 2023). "When EETs were exogenously injected into a mouse model of asthma, epithelium-derived cytokine levels (including IL-1α, IL-1β, Chemokine ligand 1 [CXCL-1], CCL24, IL-33, and TSLP) were found to be significantly increased in mouse bronchoalveolar lavage fluid (BALF)." (PMID 37752512, 2023). "This along with recent success of Tezepelumab targeting the epithelial derived thymic stromal lymphopoietin (TSLP) to improve asthma control regardless of T2 inflammation reemphasizes the cardinal role of the airway epithelium in asthma pathophysiology." (PMID 37996952, 2023). "In a murine model of asthma, protease allergens—such as papain and house dust mites (HDM)—and Aspergillus fumigatus damaged airway epithelial cells, releasing epithelial-derived cytokines such as IL-25, IL-33, and TSLP." (PMID 37371472, 2023). "The fundamental role of TSLP in asthma pathogenesis was underscored by the fact that in 2021, US FDA approved tezepelumab (Tezspire), a human monoclonal antibody (IgG2λ) that inhibits the interaction of TSLP with its heterodimeric receptor, for SA treatment." (PMID 37108740, 2023). "Four of the eight signals identified as novel (GLB1, FAM105A, PHB, TSLP) are known signals for asthma or allergic disease, but not COPD." (PMID 35104449, 2022). "The TSLP values used here to define “High TSLP levels” are only pertinent to our study group and cannot be extrapolated to other settings with potential differences in BAL retrieval and analyses, including adults with asthma." (PMID 36245744, 2022). "As with TSLP, overexpression of IL25 can induce asthma-like disease in mice." (PMID 36685501, 2022). "Unlike its receptor, TSLP expression is restricted with its primary expression site in airway epithelial cells, extending to airway smooth muscle cells and mast cells in asthma, and activating a caspase-1/NF-κB pathway." (PMID 36311787, 2022). "Few studies have examined the direct effect of TSLP on mature human eosinophils, and cross-sectional comparisons with cells from asthma patients compared with healthy controls are also lacking." (PMID 35572064, 2022). "In a subset of patients with severe asthma, TSLP expression remained enhanced, independent of treatment with high-dose ICS or OCS." (PMID 36140430, 2022). "TSLP and IL33 may be important new targets individualized for asthma treatment, and antibody-based drugs for these pathways are being developed." (PMID 36685501, 2022). "TSLP triggers allergic/eosinophilic and non-allergic/eosinophilic inflammation, and is also involved in neutrophilic inflammation in asthma." (PMID 35626330, 2022). "The expression of IL-33, IL-25, and TSLP should be higher in ABPA and asthma theoretically." (PMID 35983066, 2022). "IL33 and thymic stromal lymphopoietin (TSLP) are cytokines functioning as alarmins that are released by the airway epithelium in response to viruses, allergens and other triggers and drive type 2 responses in asthma." (PMID 36685501, 2022).
asthma (continued). "For instance, in a virus-induced HDM asthma exacerbation study, targeting TSLP did not impact anti-ST2-mediated reduction of airway inflammation." (PMID 36311787, 2022). "In contrast, increased expression of IL-33 and TSLP, but not IL-25, was reported in asthma patients in London, Poland, and New York, New York." (PMID 33945508, 2021). "Clinical trials demonstrated that tezepelumab, an anti-TSLP monoclonal antibody, is a promising alternative treatment for asthma that is effective also in nontype 2 asthma." (PMID 34608100, 2021). "Within the airways, TSLP co-localizes with ILC2, and a direct relationship has been shown between TSLP levels and ILC2 numbers in nasal biopsy samples taken from patients with chronic rhinosinusitis and severe asthma." (PMID 34572294, 2021). "IL-25 and TSLP, although not members of the alarmin family, are cytokines that act together to and share similar features with IL-33 in asthma inflammatory pathways." (PMID 34608100, 2021). "The researchers found that the expression of mRNA-encoding TSLP, TARC/CCL17, MDC/CCL22 and IP-10/CXCL10, other than I-TAC/CXCL11 and I-309/CCL1, were significantly increased in severe asthma and COPD patients compared to the non-smoking control group." (PMID 34301307, 2021). "Furthermore, in bronchial biopsy samples taken from subjects with severe asthma, ILC2 co-localized with TSLP-immunoreactive areas." (PMID 33922072, 2021). "Whatever the interpretation of these results, given the relevance of TSLP and TH2 cytokines in the pathogenesis of asthma, it is likely that these observations have translational relevance contributing to clinical manifestations of chronic inflammatory lung disorders." (PMID 34440780, 2021). "The meta-analysis identified as the 5 most significant loci on chromosomes 17q12-21 near PGAP3 and ERBB2, 6p21.32 near HLA-122 DRB1/-DQA1, 5q22.1 near TSLP, 2q12 near IL1RL1/IL18R, and 9p24.1 near IL33 in both the whole sample and in the subset that included only subjects with early-onset asthma." (PMID 33673725, 2021). "Here, in a different cohort of asthmatic patients, using ELISA and qPCR, we found that airway expression of IL-25 and TSLP, but not IL-33, was elevated in type 2–high asthma patients." (PMID 33945508, 2021). "Our data suggest that airway expression of IL-25 and TSLP, but not IL-33, is elevated in type 2–high asthma." (PMID 33945508, 2021). "Baicalein also inhibits the thymic stromal lymphopoietin (TSLP)/TSLP receptor (TSLPR) signaling pathways and may be utilized as an agent to treat asthma and atopic dermatitis." (PMID 34575592, 2021). "Moreover, the intensity of inflammation is higher in patients with obstructive lung diseases in our study, especially observed for IL-6 in COPD and IL-8 in both asthma and COPD, and include other mediators e.g., TSLP and IL-33 in asthma." (PMID 34168212, 2021). "In fact, blocking the various functions mediated by TSLP has been proven effective in reducing asthma exacerbations in both type 2 and nontype 2 asthma [36,39▪▪]." (PMID 34608100, 2021). "There are numerous biologics currently in clinical trials, the thymic stromal lymphopoietin (TSLP) mAbs in particular have shown promising results independent of the asthma phenotype." (PMID 33615123, 2021). "Thymic stromal lymphopoietin (TSLP) was initially demonstrated to be critical in regulating inflammatory responses among various allergic disorders (such as atopic dermatitis, food allergy, and asthma)." (PMID 34249003, 2021). "In Korea, plasma IL-25, but not IL-33 or TSLP, was increased in patients with aspirin-exacerbated respiratory disease characterized by asthma, nasal polyps, and chronic eosinophilic sinusitis." (PMID 33945508, 2021). "TSLP is a potent initiator of type 2 inflammatory immune responses at barrier surfaces that, if not regulated stringently, can result in asthma exacerbation." (PMID 34659250, 2021).
asthma (continued). "Co-culture with epithelium and moMφs significantly increased TSLP in asthma and did not change IL-33 and IL-17A mRNA expression in moDCs." (PMID 32842623, 2020). "We decided to show this data because for all subjects in the control group, the concentration of TSLP in the sputum did not exceed 3 pg/mL, while in the other two groups, there were only single cases (1 in the asthma and 3 in the COPD group)." (PMID 33203095, 2020). "ILC2s play a role in the production of pro-inflammatory cytokines, and overexpression of the transcription factor GATA3 increased the expression of stimulation-expressed gene 2 (ST2) and thymic stromal lymphopoietin (TSLP) receptors in the human pulmonary ILC2, leading to the development of asthma." (PMID 33339172, 2020). "We found that co-culture with epithelium and moMφs significantly increased TSLP mRNA in the asthma group and to a lesser extent or did not change IL-33 and IL-17A mRNA expression in moDCs." (PMID 32842623, 2020). "Secretion of TSLP from airway epithelial cells can drive expansion of type 2 innate lymphoid cell (ILC2) expansion and mucus metaplasia during experimental RV infection in baby mouse model of asthma." (PMID 32637363, 2020). "There were neither significant correlations between serum periostin and TSLP levels in asthma nor IS or serum periostin and TSLP levels (or their mRNA expression) in the COPD and control groups." (PMID 33203095, 2020). "Collectively, administration of YPFS in remission prominently alleviated HDM-induced asthma relapse by restoring DSG1 and decreasing TSLP overexpression, which might be the key factors contributing to chronic asthma relapse." (PMID 32076408, 2019). "Thus, a TSLP-DC-OX40L pathway was formed and promoted airway inflammation and asthma pathogenesis by increasing inflammatory cytokines and decreasing CD4 + CD25 + Treg cells." (PMID 30890137, 2019). "In addition to IL-17, some cytokines, including thymic stromal lymphopoietin (TSLP), IL-33 and IL-25, are key factors for the development of allergic diseases, such as asthma and skin atopic dermatitis, that act by promoting Th2-type responses." (PMID 31805177, 2019). "TSLP is a four-helix bundle cytokine that can activate DCs, NKT cells, mast cells, and eosinophils to interact with cytokines and inflammatory mediators on the airway smooth muscle of patients with asthma." (PMID 31284537, 2019). "TSLP appears to be an important common pathway between airway epithelium and inflammatory cascades and counts of ILC1 cells, such as NK cells, have been found to be low in patients with severe asthma." (PMID 31856838, 2019). "The thymic stromal lymphopoietin (TSLP)/TSLP receptor (TSLPR) axis plays an important role in the regulation of a broad spectrum of inflammatory immune response-related diseases, including asthma and CAD." (PMID 30123216, 2018). "Studies have evaluated the role of the TSLP and TSLPR heterocomplex in asthma." (PMID 29670037, 2018). "The TSLP–TSLPR heterocomplex axis is involved in innate–adaptive immunity; the TSLPR heterocomplex may be an early biomarker of the development of asthma and therefore warrants further investigation." (PMID 29670037, 2018). "We believe that further integrated assessments of the regulation mechanism of the TSLP–TSLPR heterocomplex axis in vitro and in vivo can provide a faster and earlier diagnosis of pediatric asthma and promote the development of more effective preventive strategies at the onset of allergies." (PMID 29670037, 2018). "The epithelium controls the local immune activities of IgA antibodies, defensins, and lysozymes, which are also regulated by the production of IL-25, IL-33, and thymic stromal lymphopoietin (TSLP), that in turn stimulate a Th2 type inflammation, which is known to favor the development of asthma." (PMID 30598019, 2018). "The mRNA expression of TSLP, IL-25 and IL-33 was significantly higher in patients with severe asthma and CRS compared to those of non-severe asthma with CRS." (PMID 28199345, 2017).
asthma (continued). "TSLP is an epithelial IL7-like cytokine activating Th2 responses, and is responsible for a pattern of inflammation suggestive of multimorbidity between asthma and chronic obstructive pulmonary disease, and between different types of dermatitis." (PMID 28598986, 2017). "In contrast, the expression of TSLP, IL-25, and IL-33 in non-severe asthma patients with CRS group was very weak (respectively)." (PMID 28199345, 2017). "In severe asthma patients with CRS, there was an upregulated expression of IL-33, IL-25 and TSLP in their nasal tissues, compared to those in non-severe asthma patients." (PMID 28199345, 2017). "In mice, it could be shown that the expression of TSLP, IL4, IL5 and IL13 induces atopic dermatitis as well as asthma, and IL5 knockout mice exposed to allergens are less prone than wild-type to develop skin eosinophilia and epidermal thickening." (PMID 27431613, 2016). "However, this is the first attempt to illustrate the positive relationship between TSLP neutralization and the adjuvant effect of DEHP in a mouse model of asthma." (PMID 27467143, 2016). "Additionally, because TSLP acts upstream of TH2-associated cytokine and IgE production, it may potentially act as a “master switch” in that inhibiting its actions may shut down multiple components of the TH2 response responsible for the initiation of asthma pathogenesis." (PMID 27378934, 2016). "In addition to CCL11/eotaixn-1 and TNF-alpha, HBEC exposed to TSLP induced the secretion of CCL22/MDC and CCL17/TARC, two CCR4-ligands that are considered critical Th2-related chemokines in asthma exacerbations." (PMID 25546419, 2014). "Although TSLP and CCL11/eotaxin-1 play a critical role in the pathogenesis of asthma, it is noteworthy that TSLP alone was not enough to induce CCL11/eotaxin-1 in control HBEC." (PMID 25546419, 2014). "In mice, TSLP overexpression led to spontaneous airway inflammation and an asthma phenotype, whereas mice lacking the TSLP receptor (TSLPR) exhibited substantially blunted allergic airway inflammation." (PMID 23300949, 2013). "This activation in turn increased the production of IL-33, IL-25, and thymic stromal lymphopoietin (TSLP); raising the possibility that resident ILCs2 might be activated by these stroma-derived cytokines in HDM-induced asthma." (PMID 23209480, 2012). "At 5q22.1, TSLP and WDR36 were proposed to be candidate genes for asthma in Caucasian population." (PMID 22545103, 2012). "Therefore, RBP-jCKO;IL7rα-/- animals provide a suitable system in which to determine if skin-barrier defects and AD-like skin inflammation including a systemic Th2 response with its consequences (e.g., elevated IgE) could confer susceptibility to asthma in the absence of TSLP signaling." (PMID 19557146, 2009). "Since TSLP expression is blocked by a PIN1 inhibitor after challenging lung with allerges and the 3'-untranslated region of TSLP mRNA contain an AUF1 binding site, PIN1 is likely to be a modulator of TSLP expression in asthma at the posttranscriptional level." (PMID 18724870, 2008). "Tezepelumab, a human monoclonal antibody targeting TSLP, represents the first biologic approved for severe asthma without phenotype- or biomarker-restricted eligibility, including type 2-low disease, with the caveat that the magnitude of benefit is somewhat smaller in T2-low patients." (PMID 42110556, 2026). "Interestingly, Louise′s study revealed that the involvement of TSLP in AHR among asthma patients is independent of eosinophilic inflammation, implying its participation in non‐T2 inflammation as well." (PMID 41568067, 2026). "Unlike TSLP, IL-33 plays a key role in driving virus-induced exacerbations in asthma patients." (PMID 41169790, 2025). "In addition, asthmatic populations varied across included studies in terms of asthma phenotypes (e.g., atopic vs. non-atopic), disease severity (mild vs. severe asthma), and age (children vs. adults), potentially influencing TSLP levels." (PMID 41357156, 2025).
asthma (continued). "Single blockade of TSLP, IL-25, or IL-33, which stimulate ILC2 and Th2 cells to release type 2 cytokines, decreases airway inflammation and hyperresponsiveness in murine asthma models, and concurrent blockade of all three cytokines produces more pronounced effects." (PMID 39962262, 2025). "Moreover, TSLP concentrations in induced sputum (n = 71) and bronchoalveolar lavage fluid (n = 85) from patients with asthma also exhibited non-normal, right-skewed distributions." (PMID 41357156, 2025). "Indeed, targeting alarmins during asthma has shown great potential, with a range of novel biologics currently in clinical trials for asthma, such as itepekimab targeting IL‐33, astegolimab targeting IL‐33 receptor ST2, or tezepelumab targeting TSLP." (PMID 39991870, 2025). "In contrast to prior studies, which focused primarily on TSLP as a therapeutic target rather than a predictive biomarker, our study provides new insights into TSLP’s potential role in immune resolution and disease trajectory in pediatric asthma." (PMID 40503233, 2025). "Recently approved or therapeutic trials of monoclonal antibodies against TSLP, IL-33 and its receptor ST2, or mast cells validate the roles of these upstream drivers of type 2 inflammation in asthma; however, they also display efficacy in people with severe asthma who lack T2 features." (PMID 40047886, 2024). "Overproduction of TSLP in asthma epithelium when exposed to viral double-stranded RNA may explain more severe viral pneumonia when compared to patients without asthma, although this response depends on the virulence and features of the virus itself." (PMID 38672419, 2024). "However, the question of whether these differences relate to asthma severity or response to asthma medications, such as ICS and anti-TSLP therapy, requires investigation." (PMID 38672419, 2024). "Collectively, our results demonstrate that CUL5, which is upregulated by the epithelial alarmin TSLP in allergic asthma, can contribute to the “insensitive” state of AMs by inhibiting IFN-β production following the viral infection and driving the development of virus-induced asthma exacerbations." (PMID 38177117, 2024). "Collectively, our results indicate that TSLP in the allergic asthma microenvironment can induce a CUL5-mediated inhibitory effect on antiviral immunity, which may contribute to the exacerbations of asthma." (PMID 38177117, 2024). "In asthma, both allergic and nonallergic triggers induce TSLP production." (PMID 39685611, 2024). "Ten-year results suggest that TSLP could be a cytokine of interest in non-severe asthma and non-allergic asthma as a predictive marker of later asthma persistence, suggesting TSLP is a potential biomarker to monitor asthma evolution in adults." (PMID 38731070, 2024). "Several publications have shown that a TSLP/ILC axis may play a pivotal role in steroid-resistant allergic airway inflammation, very important in the treatment of asthma." (PMID 38529406, 2024). "Furthermore, in a mouse model of asthma, ST2 knockout reduced airway inflammation, Th2 cytokine expression and fibrosis-related protein deposition, all of which were further reduced by additional blockade with anti-TSLP and anti-IL-25 antibodies." (PMID 38609094, 2024). "In this regard, the clinical efficacy of TSLP blockade in severe asthma patients could not be solely explained by the effects of the anti-TSLP mAbs on DCs and Th2 cells." (PMID 38566968, 2024). "Currently, several inhaled antibody fragments targeting, e.g., thymic stromal lymphopoietin (TSLP), tumor necrosis factor receptor 1 (TNFR-1), and interleukin-13 (IL-13), are under clinical investigation for the treatment of pulmonary diseases, particularly asthma." (PMID 37514028, 2023).